SLC25A1 (solute carrier family 25 member 1)
Diseases named in the same sentence as SLC25A1 in open-access papers (continued):
Sharing a sentence is not in itself a finding about the gene and the disease.
Intellectual disability (4 papers, 2020 to 2023). "We previously identified a homozygous c.740G>A; p.(Arg247Gln) missense variant in SLC25A1 in a British sib-pair presenting with a mild form of CMS with intellectual disability." (PMID 31527857, 2020). "Our findings suggest that SLC25A1 and in particular the p.(Arg247Gln) variant should also be considered in CMS cases with intellectual disability." (PMID 31527857, 2020). "In summary, the p.(Arg247Gln) SLC25A1 variant should be considered in patients presenting with a presynaptic CMS, particularly with accompanying intellectual disability." (PMID 31527857, 2020). "In conclusion, the p.(Arg247Gln) SLC25A1 variant should be considered in patients presenting with a presynaptic CMS phenotype, particularly with accompanying intellectual disability." (PMID 31527857, 2020). "In addition to fatigable muscle weakness and ptosis, both TEFM and SLC25A1 CMS-like patients have been reported to have intellectual disabilities and/or learning difficulties, which is uncommon in CMS patients." (PMID 37239850, 2023). "We previously reported a single family with a homozygous missense variant in SLC25A1 with a phenotype restricted to relatively mild CMS with intellectual disability, but to date no additional cases of this CMS subtype had been reported." (PMID 31527857, 2020). "Genetic analysis performed in these unrelated families revealed that patients had distinct haplotypes, proving that the R247Q SLC25A1 variant is not a founder effect, rather it is the result of a recurrent mutation associated with a relatively mild CMS phenotype implying intellectual disability." (PMID 34827632, 2021).
fatty liver disease (3 papers, 2020 to 2022). A reversible condition wherein large vacuoles of triglyceride fat accumulate in liver cells via the process of steatosis. "Recent study reported that Slc25a1 serves as an important player in the pathogenesis of fatty liver disease and ﻿high-fat diet-induced obesity." (PMID 35585086, 2022). "In summary, our data show for the first time that Slc25a1 serves as an important player in the pathogenesis of fatty liver disease and thus, provides a potentially exploitable and novel therapeutic target." (PMID 31959914, 2020). "In all, these results suggested a role for Slc25a1 in fatty liver disease." (PMID 31959914, 2020).
liver cancer (3 papers, 2023 to 2025). An epithelial or non-epithelial malignant neoplasm that arises from the liver. "IDH2 and SLC25A1 in liver cancer were found to have a positive Spearman correlation (R = 0.20, P = 1.931e-4)." (PMID 37741815, 2023). "Noticeably, we discovered that SLC25A1 mRNA levels in T3A-A3 cells were increased dramatically than in liver cancer cell lines MHCC97H and Huh7." (PMID 37741815, 2023). "Using the UALCAN database, we found that SLC25A1 mRNA levels were dramatically upregulated in HCC than in normal tissues and that LCSCs had significantly higher levels of SLC25A1 expression than liver cancer cell lines." (PMID 37741815, 2023). "The study puts forward a new view that regulating SLC25A1 is an encouraging therapeutic target for treating liver cancer and suggests that PTL may be a valid candidate natural agent to eliminate LCSCs." (PMID 37741815, 2023). "As has been reported in CRC36, high SLC25a1 expression suggests that enhanced citrate export may facilitate increased de novo lipogenesis in liver cancer." (PMID 37798427, 2023). "However, the roles of SLC25A1 in the abnormal energy metabolism and pathogenesis of liver cancer have not been adequately studied." (PMID 37741815, 2023).
lung adenocarcinoma (3 papers, 2018 to 2025). A carcinoma that arises from the lung and is characterized by the presence of malignant glandular epithelial cells. "Meanwhile, SLC25A1 was linked to clinical outcomes across multiple tumor types, particularly in lung adenocarcinoma, where its high expression predicted poor prognosis." (PMID 37981593, 2023). "To confirm the function of SLC25A1 in tumor growth, we selected lung adenocarcinoma cell lines to examine the effect of SLC25A1 knockdown on cell proliferation in vitro." (PMID 37981593, 2023). "The expression of SLC25A1 increased in most cancers, and the upregulation of SLC25A1 in colon adenocarcinoma and lung adenocarcinoma was further confirmed by immunohistochemistry." (PMID 37981593, 2023). "Cellular experiments showed that SLC25A1 knockdown significantly reduced the proliferation of lung adenocarcinoma cells." (PMID 37981593, 2023). "The colony formation assays demonstrated that SLC25A1 knockdown markedly suppressed the proliferation of lung adenocarcinoma cells." (PMID 37981593, 2023). "Moreover, Kaplan–Meier survival analysis indicated that patients with high SLC25A1 and ACLY expression in skin cutaneous melanoma (SKCM) and lung adenocarcinoma (LUAD) had shorter survival than those with low SLC25A1 and ACLY expression." (PMID 39881208, 2025). "Intriguingly, further analysis showed that SLC25A1 was associated with a poor prognosis in lung adenocarcinoma, but was not correlated to OS or FP in lung squamous cell carcinoma." (PMID 37981593, 2023).
lymphoma (3 papers, 2021 to 2024). A malignant (clonal) proliferation of B- lymphocytes or T- lymphocytes which involves the lymph nodes, bone marrow and/or extranodal sites. "Overall, lymphomas were most vulnerable to SLC25A1 knockout, specifically SUDHL10 and SUDHL5 diffuse large B-cell lymphoma (DLBCL) cell lines." (PMID 37981593, 2023). "The inhibitors intended to target metabolic enzymes, such as SLC25A1 (CPT1), MCT1 (MCT-III), LDHA (oxamate), glutamine transporter (MK801), and PDH/α-ketoglutarate (Demvistat), without affecting cell viability in the lymphoma cells or LCL." (PMID 39518046, 2024).
non-small cell lung carcinoma (3 papers, 2018 to 2024). A group of at least three distinct histological types of lung cancer, including non-small cell squamous cell carcinoma, adenocarcinoma, and large cell carcinoma. "Previous studies have shown that SLC25A1 directly regulates mitochondrial function and plays a crucial role in maintaining the mitochondrial pool and the redox equilibrium of citric acid in non-small cell lung cancer." (PMID 39329971, 2024). "Additionally, SLC25A1 inhibitor was synthetic lethal with the EGFR inhibitor AZD9291 in non-small cell lung cancer both in vitro and in animal models." (PMID 37981593, 2023).
epilepsy (2 papers, 2017 to 2019). A brain disorder characterized by episodes of abnormally increased neuronal discharge resulting in transient episodes of sensory or motor neurological dysfunction, or psychic dysfunction. "Epilepsy was reported in patients with CMS due to SLC25A1 mutations, due to MUNC13–1 mutations, or due to ALG14 mutations." (PMID 30808424, 2019). "Loss of function of either SLC13A5 or SLC25A1 causes epilepsy even though the consequences of their loss of function on mitochondrial citrate levels are opposite." (PMID 28264506, 2017). "These arguments question the validity of the idea that defects in SLC25A1 cause epilepsy because of decreased energy production." (PMID 28264506, 2017). "Furthermore, loss-of-function mutations in the mitochondrial citrate transporter (SLC25A1) also cause epilepsy." (PMID 28264506, 2017).
glioblastoma (2 papers, 2018 to 2022). The most malignant astrocytic tumor (WHO grade IV). "Of note, SLC25A1 inhibition enhanced vulnerability to DNA repair inhibitors of EJ-pathways in irradiated lung and glioblastoma cell line models, without IDH1/2 mutations." (PMID 35869047, 2022). "Here, we selected lung and glioblastoma cell lines without described mutation in IDH to investigate if treatment with a more specific 3rd generation small molecule SLC25A1 inhibitor CTPI2 would induce D-2-HG accumulation and mimic the HR-ness phenotype of IDH1/2 deficient cells." (PMID 35869047, 2022). "Therefore, we downregulated the expression of SLC25A1 by siRNA-technology (RNAi) and determined the effects on D-2-HG levels in lung (A549, NCI-H460) and glioblastoma (U87-MG, T98G) cell lines." (PMID 35869047, 2022).
Hyperglycemia (2 papers, 2020 to 2024). An increased concentration of glucose in the blood. "Proteomics and transcriptomics data showed that SLC25A1 was increased in normoglycemia in MIC26 KOs (compared with respective WT) but not in hyperglycemia." (PMID 39393820, 2024).
Insulin resistance (2 papers, 2025 to 2026). Increased resistance towards insulin, that is, diminished effectiveness of insulin in reducing blood glucose levels. "Reduced expression of lipogenesis genes such as Slc25a1 in these mice may also contribute to insulin resistance, because insulin resistance is associated with reduced lipogenesis enzyme expression in WAT6." (PMID 40196683, 2025).
melanoma (2 papers, 2023 to 2025). A malignant, usually aggressive tumor composed of atypical, neoplastic melanocytes. "To further validate the clinical relevance of our findings, we analyzed a tissue microarray (TMA) comprising 111 tumor samples from melanoma patients to assess the expression of SLC25A1, ACLY, and FSP1 using multiplex immunofluorescence (mIF) staining." (PMID 39881208, 2025).
neuroblastoma (2 papers, 2023 to 2025). Neuroblastoma (NB) is the most common solid, extracranial childhood tumor. "To exclude that an APOE expression increase was a haploid HAP1 cell peculiarity, we confirmed the increased levels of APOE in the diploid human neuroblastoma cell line SH-SY5Y where we CRISPRed out the SLC25A1 gene (Figure 2CSLC25A1Δ/Δ)." (PMID 37171075, 2023). "We used an orthogonal SLC25A1 dataset obtained from SH-SY5Y neuroblastoma cells to further test the hypothesis that the network of proteins regulated by SLC25A1 influences cognition." (PMID 37171075, 2023). "However, these phenotypes were not shared by SLC25A1-null neuroblastoma cells or SLC25A4-null cells, even though these cells also displayed increased APOE expression and secretion." (PMID 37171075, 2023).
citrin deficiency (1 paper, 2023). "Another rare cause of elevated citrate levels is citrin deficiency, which is characterized by aspartate/glutamate carrier deficiency and upregulation of mitochondrial citrate/isocitrate carrier (CiC, also known as SLC25A1) leading to citrin deficiency." (PMID 37686138, 2023).
cognitive decline (1 paper, 2023). "In line with this reasoning, we found that greater expression of proteins belonging to the SLC25A1 interactome strongly correlated with a rapid cognitive decline in the Banner cohort (r=−0.527, p<9.92e-08)." (PMID 37171075, 2023).
developmental delay (1 paper, 2020). "Variants in the SLC25A1 gene are associated with a severe neurometabolic disease, D-2- and L-2-hydroxyglutaric aciduria (D/L-2-HGA), which is characterized clinically by severe developmental delay, hypotonia, and seizures." (PMID 32660532, 2020). "Given the combination of his clinical phenotype (fatigable muscular weakness, myasthenic crisis, epilepsy, developmental delay, mild elevation of 2-KG and lactic acid in urine) and the molecular genetic findings, the proband was diagnosed with SLC25A1-related disorder." (PMID 32660532, 2020).
endometriosis (1 paper, 2026). The growth of functional endometrial tissue in anatomic sites outside the uterine body. "Meanwhile, in vitro and in vivo experiments demonstrated that cholesterol supplementation reversed the cellular and immune microenvironment alterations caused by SLC25A1 knockdown, further confirming the critical role of SLC25A1 in the endometriosis progression mediated by cholesterol metabolism." (PMID 41362733, 2026). "Our results suggest that SLC25A1 is a key target in the regulation of cholesterol metabolism and endometriosis progression." (PMID 41362733, 2026). "SLC25A1 upregulates cholesterol metabolism in ESCs and directly exacerbates endometriosis deterioration." (PMID 41362733, 2026). "Overall, these results strongly suggested that SLC25A1 drives M2 macrophage polarization and endometriosis progression, with cholesterol metabolism being a key regulator of this process." (PMID 41362733, 2026). "To verify whether SLC25A1 promoted the progression of endometriosis by upregulating cholesterol metabolism, we conducted rescue experiments by supplementing the shSLC25A1 group with cholesterol." (PMID 41362733, 2026). "We investigated the biological effects of SLC25A1 in the context of endometriosis." (PMID 41362733, 2026). "Consequently, disrupting the pernicious cycle involving SLC25A1-mediated cholesterol accumulation in ESCs and cholesterol-induced M2 macrophage polarization may lead to new breakthroughs in endometriosis therapy." (PMID 41362733, 2026). "Furthermore, we identified solute carrier family 25 member 1 (SLC25A1) as a pivotal target for regulating cholesterol metabolism in endometriosis, as it significantly upregulated in ectopic lesions and markedly increased intracellular and extracellular cholesterol content." (PMID 41362733, 2026). "In terms of cellular function, SLC25A1 significantly promoted proliferation, migration and invasion of HESCs, and drove macrophage polarization towards the M2 phenotype via the regulation of cholesterol metabolism, creating a favorable immune microenvironment for endometriosis progression." (PMID 41362733, 2026). "Additionally, the partial rescue effects of exogenous cholesterol supplementation indicate that while cholesterol metabolism is a key SLC25A1-regulated downstream pathway in endometriosis, it may not be the sole mediator of the biological functions of SLC25A1." (PMID 41362733, 2026).
fibrosarcoma (1 paper, 2025). A malignant mesenchymal fibroblastic neoplasm affecting the soft tissue and bone. "Consistent with this notion, the levels of D-2HG in fibrosarcoma cells, HT-1080, which harbor one of the most common IDH1 mutations, IDH1R132C, were more than 30 fold higher compared to cells harboring the SLC25A1-KD." (PMID 39733217, 2025).
Graves disease (1 paper, 2024). Graves' disease is an autoimmune disorder that leads to overactivity of the thyroid gland (hyperthyroidism).It is caused by an abnormal immune system response that causes the thyroid gland to produce too much thyroid hormones. "The analysis identified several mitochondrial proteins downregulated by HFD, including the citrate carrier (SLC25A1), the dicarboxylate acid carrier (SLC25A10), a glutamate carrier (SLC25A22), and a carrier associated with Graves’ disease (SLC25A16)." (PMID 39111307, 2024).
L-2-hydroxyglutaric aciduria (1 paper, 2023). L-2-hydroxyglutaric aciduria is a primarily neurological form of 2-hydroxyglutaric aciduria characterized by psychomotor retardation, cerebellar ataxia and variable macrocephaly or epilepsy. "Combined D, L-2-Hydroxyglutaric Aciduria (D,L-2HGA) is a rare genetic disorder caused by recessive mutations in the SLC25A1 gene that encodes the mitochondrial citrate carrier protein (CIC)." (PMID 36778323, 2023).
metastatic tumor (1 paper, 2021). "Consistent with our observations in CRC, a previous study in non-small cell lung cancer (NSCLC) also demonstrated that SLC25A1 expression is higher in primary and metastatic tumor tissues than in matched normal adjacent tissues." (PMID 34839347, 2021).
microcephaly (1 paper, 2025). A congenital or acquired developmental disorder in which the circumference of the head is smaller than normal for the person's age and sex. "The clinical spectrum of manifestations associated with SLC25A1 gene mutations in D/L-2HGA is severe, consisting of craniofacial abnormalities, facial dysmorphic features, micrognathia or retrognathia, and microcephaly or macrocephaly." (PMID 39733217, 2025).
non-alcoholic steatohepatitis (1 paper, 2025). "Meanwhile, as a specific inhibitor of SLC25A1, CTPI-2 significantly mitigates lipid metabolism disorders in non-alcoholic steatohepatitis (NASH), thereby impeding its progression to hepatic steatosis and reducing inflammatory macrophage infiltration in the liver and adipose tissue." (PMID 40028341, 2025).
progeria (1 paper, 2023). "Finally, our results indicate that SLC13A5-derived citrate is tightly linked to ER proteostasis and associated progeria, while SLC25A1-derived citrate is not." (PMID 37689798, 2023). "Both animals displayed increased cytosolic levels of citrate and acetyl-CoA; however, SLC13A5 sTg mice developed a progeria-like phenotype with premature death, while SLC25A1 sTg mice did not." (PMID 37689798, 2023).
squamous carcinomas (1 paper, 2018). "Nearly all adenocarcinomas and squamous carcinomas were immunoreactive for SLC25A1, unlike the normal respiratory epithelium." (PMID 29651165, 2018).